L1CAM (L1 cell adhesion molecule)
Diseases named in the same sentence as L1CAM in open-access papers (continued):
Sharing a sentence is not in itself a finding about the gene and the disease.
retinopathy (2 papers, 2015 to 2017). "In blood, we are the first to show that a significantly higher L1CAM, but normal PIP, THBS2 or NGAL level was associated with retinopathy of T2DM." (PMID 27446820, 2015). "Also, T2DM patients with retinopathy have normal THBS2, NGAL and PIP levels but a significantly higher L1CAM level." (PMID 27446820, 2015). "Also, T2DM patients with retinopathy have normal THBS2, NGAL and PIP levels but elevated L1CAM levels." (PMID 27446820, 2015).
cardiac diseases (1 paper, 2021). "Further studies on the precise molecular mechanisms underlying the role of vascular L1CAM in DNA damage will aid in the development of novel therapeutic strategies for cardiac diseases." (PMID 34078883, 2021).
L1CAM also shares sentences with these, for which no sentence is quoted: renal cell carcinoma (8 papers); Aphasia (6); neuroendocrine tumors (6); Parkinson (6); gastrointestinal stromal tumor (5); multiple sclerosis (4); renal carcinoma (4); amyotrophic lateral sclerosis (3); colorectal tumor (3); corpus callosum agenesis (3); genetic disorder (3); lung (3); neural tumors (3); neurodevelopmental disorder (3); small cell lung carcinoma (3); type 2 diabetes (3); Adducted thumbs) syndrome (2); anaplastic thyroid carcinoma (2); autism spectrum disorder (2); cyst (2); embryonal carcinoma (2); Endometrial Adenocarcinoma (2); endometrioid endometrial adenocarcinoma (2); fibrosarcoma (2); gastric adenocarcinoma (2); gynecological cancer (2); head and neck cancer (2); hereditary spastic paraplegia (2); liposarcoma (2); Lynch syndrome (2).
A further 120 diseases each share a sentence with L1CAM in 2 papers or fewer.